ZNF148 (zinc finger protein 148)
Diseases named in the same sentence as ZNF148 in open-access papers (continued):
Sharing a sentence is not in itself a finding about the gene and the disease.
lymph node metastasis (1 paper, 2024). "Moreover, ZNF148 act as a prognostic factor as its low expression is significantly associated to lymph node metastasis, poor differentiation, higher rate of disease recurrence, worse overall survival (OS) and shorter disease-free survival." (PMID 38987822, 2024).
malaria (1 paper, 2021). Malaria is a serious and sometimes fatal disease caused by a parasite that commonly infects a certain type of mosquito which feeds on humans. "The severe malaria K-TSPs model identified ten gene pairs capable of differentiating severe from non-severe malaria including: SLC38A2-SCML1, SLC25A40-MAP2K7, DNALI1-AGPAT3, LIFR-TBCD, STK17B-ORC2, SF3B1-USP48, ZNF148-ZCCHC2, CBX5-CHAF1A, CNOT7-PLXNA2, and CREM-IDH1." (PMID 34746025, 2021).
myelogenous leukemia (1 paper, 2022). "We recently reported similar GC-rich DNA consensus motifs, unique and overlapping chromatin occupancy sites for ZNF148 and ZNF281, and their functional redundancy in myelogenous leukemia cells." (PMID 36207293, 2022).
pancreatic cancer (1 paper, 2023). "Differential ZNF148 binding to the rs36115365 SNP was particularly intriguing because it is located 18 kb upstream of the 5′-end of TERT, and ZNF148 mRNA knockdown in a panel of pancreatic cancer cell lines resulted in reduced TERT expression." (PMID 37918959, 2023).
progressive neurodegenerative disorder (1 paper, 2023). "In research for HD, as well as a progressive neurodegenerative disorder, the researchers described that ZNF148 directly interacted with three known-HD genes (BCL2, CASP6, and IRS2)." (PMID 37360784, 2023).
renal carcinoma (1 paper, 2026). A carcinoma arising from the epithelium of the renal parenchyma or the renal pelvis. "In conclusion, ARDAP@SPION-PEI induces mRCSC PANoptosis by remodeling chromatin structure to promote ZNF148-mediated transcription, offering a promising epigenetic-based nanotherapeutic strategy for renal cancer." (PMID 42138776, 2026).
rhabdomyosarcoma (1 paper, 2017). A rare aggressive malignant mesenchymal neoplasm arising from skeletal muscle. "Aberrant or unregulated ZNF148 expression may contribute to diseases of muscle differentiation, such as rhabdomyosarcoma." (PMID 28811660, 2017).
triple-negative breast carcinoma (1 paper, 2022). An invasive breast carcinoma which is negative for expression of estrogen receptor (ER), progesterone receptor (PR), and human epidermal growth factor receptor 2 (HER2). "Depletion of ZNF148 by short hairpin RNA (shRNA) and CRISPR/Cas9 increased triple-negative breast cancer (TNBC) cell proliferation and migration." (PMID 36207293, 2022).
tumor (21 papers, 2014 to 2026). "ZNF148 has been linked to various cellular processes, such as cell proliferation, differentiation, and programmed cell death, and has been identified as a potential tumor suppressor." (PMID 37360784, 2023). "Consistently, cancer patients with lower ZNF148 expression in tumor-infiltrating CD8+ T cells showed improved responsiveness to immunotherapies." (PMID 41896465, 2026). "Especially, Zinc Finger Protein 148 (ZNF148) expression is significantly elevated in ESCC tumor tissues compared to adjacent normal mucosa." (PMID 41020579, 2025). "ZNF148 (also known as ZBP89, ZBP‐89, or ZFP148), a multifunctional zinc finger transcription factor involved in the regulation of cell proliferation and death, is highly expressed in tumor cells." (PMID 40085529, 2025). "Previous studies indicate that ZNF148 potentially acts as a tumor‐promoting factor in many tumors, so the implications of ZNF148 in tumor development in the context of genetics are worthy of further investigation." (PMID 37063077, 2023). "The tumorigenicity assay indicated an obvious decrease in subcutaneous tumor volumes when ZNF148 was knocked down in t‐DCs compared with the control group, while ZNF148 overexpression exerted the opposite effects." (PMID 37063077, 2023). "Collectively, these results suggest that ZNF148 mediates its tumor suppressor activities via a transcriptional and epigenetic mechanism to restrict cellular proliferation." (PMID 36207293, 2022). "Consistent with the in vitro observations, the ZNF148-overexpressing MDA-MB-231-Luc-ZNF148OE cells showed significantly reduced tumor growth in mice compared to the controls." (PMID 36207293, 2022). "To understand the molecular basis for the tumor suppressor activities of ZNF148, we investigated the transcriptional targets of ZNF148." (PMID 36207293, 2022). "In malignant tumors, ZNF148 has been reported to be a suppressive or oncogenic factor, depending on the tumor cell of origins and tissue types." (PMID 36207293, 2022). "It was also reported that ZNF148 is a novel tumor suppressor and a potential prognostic biomarker in HCC." (PMID 36380369, 2022). "Our current study supports a role for ZNF148 as a tumor suppressor gene in metastatic TNBC, that is actively repressed by MYC." (PMID 36207293, 2022). "It is a potential target in cancer therapy as experiments show that ZNF148 is a tumor suppressor capable of enhancing the killing effects of several anti-cancer drugs." (PMID 25151146, 2014). "There are many controversies regarding the role of ZNF148 in regulating tumor development." (PMID 41020579, 2025). "Multivariate Cox regression analysis confirmed that ZNF148 is an independent prognostic marker, suggesting that it may facilitate tumor progression and serve as a valuable biomarker for predicting clinical outcomes in ESCC patients." (PMID 41020579, 2025). "The tumorigenicity assay indicated an obvious decrease in subcutaneous tumor volumes when ZNF148 was knocked down in t‐DCs, and this effect could be partially reversed by the simultaneous upregulation of PTX3." (PMID 37063077, 2023). "Tumor‐bearing nude mouse was used to evaluate tumorigenesis of ZNF‐148." (PMID 37909239, 2023). "Finally, ZNF‐148‐overexpressing and ZNF‐148‐deficient T47D cells were used to establish xenograft tumor‐bearing mouse models, which demonstrated that ZNF‐148 promoted tumorigenesis in vivo." (PMID 37909239, 2023). "Besides, intracellular expression of ZNF148 and PTX3 increased obviously in tumor‐associated astrocytes (TAAs) at both transcriptional and protein levels, compared with NHAs." (PMID 37063077, 2023). "It is possible that the tumor suppression by BRCA1 may be in part mediated by ZNF148 activation as a result of MYC downregulation." (PMID 36207293, 2022). "Collectively, these data support a tumor suppressive role for ZNF148 in TNBC cells." (PMID 36207293, 2022).
tumor (continued). "Although ZNF148 has been speculated as a tumour suppressor gene, up-regulated expression was observed at steps towards carcinogenesis in familial adenomatous polyposis." (PMID 28580939, 2017). "GBM stem-like cells can further drive malignant DC transformation via ZNF148/PTX3 signaling, while tumor-derived exosomes induce ferroptosis in DCs through modulation of the NRF2/glutathione peroxidase-4 (GPX4) pathway, contributing to tumor progression." (PMID 40948940, 2025). "Our studies identified a common characteristic genetic profile of benign nodules, mutually exclusive mutation of SPOP, ZNF148 and EZH1 was observed in 24.3% of the adenomatoid nodules but not in matched PTC tumours." (PMID 28580939, 2017). "The differential expression of hsa_circRNA_0101125, miR‐143‐3p, and ZNF148 between the two cell lines implies that while this axis is functionally relevant in ESCC, its regulatory strength or expression dynamics may vary with tumor location." (PMID 41020579, 2025).
cancer (20 papers, 2013 to 2026). A tumor composed of atypical neoplastic, often pleomorphic cells that invade other tissues. "The study conducted revealed a significant association between ZNF148 and the expression of PD-L1 and the PD-1 checkpoint pathway in cancer." (PMID 37360784, 2023). "Through quantitative mass spectrometry, we identified preferential binding of zinc finger protein 148 (ZNF148, also named ZBP-89) to the C-allele of rs36115365 in multiple cancer cell lines, and ChIP data confirmed binding of ZNF148 over rs36115365." (PMID 28447668, 2017). "Notably, our data suggest that the mechanism by which ZNF148 influences TERT is similar for cancer types in which the C-allele of rs36115365 contributes to increased risk, or alternatively to disease protection." (PMID 28447668, 2017). "ZNF148 is a transcription factor whose downregulation seems to be a recurring event in different human cancers." (PMID 38987822, 2024). "Global transcriptome and chromatin occupancy analyses of ZNF148 revealed a central role in inhibiting cancer cell de-differentiation and migration." (PMID 36207293, 2022). "As ZNF148 suppresses stemness in MDA-MB-231 cells, we reasoned that certain target gene(s) of ZNF148 promoting stemness in cancer cells, are repressed by ZNF148." (PMID 36207293, 2022). "Mechanistically, we identified the Inhibitor of DNA binding 1 and 3 (ID1, ID3), drivers of cancer stemness and plasticity, as previously uncharacterized targets of transcriptional repression by ZNF148." (PMID 36207293, 2022). "The median CRISPR and siRNA scores for ZNF148 were 0.05 (± 0.01 95% CI) and − 0.12 (± 0.02 95% CI), suggesting that cancer cells are marginally affected by ZNF148 inactivation." (PMID 32843651, 2020). "Three other genes with p9 or p11 missense mutations, ZNF281, ZNF148 (ZBP89), and ZEB1, have also been identified as ZF genes important in cancer onset and progression." (PMID 29953437, 2018). "ZBP89 (C2H2-type, transcription factor), also known as ZNF148, is a well-characterized zinc-finger factor involved in cancer growth and apoptosis." (PMID 29152378, 2017). "Based on these contradictory findings, we speculated that ZNF‐148 has a double‐edged effect of promoting cancer cell proliferation and inhibiting proliferation depending on its different phenotypes." (PMID 37909239, 2023). "Moreover, the negative regulation of ZNF148 on stemness in HCC indicates its potential as a novel target to reverse cancer stem cell (CSC)-induced drug resistance." (PMID 36380369, 2022). "Interestingly, the data suggests that Znf148 may play a different role in advanced CRC since Znf148 expression in carcinomas was inversely correlated with TNM stage and patient survival." (PMID 27487143, 2016). "MYC actively represses ZNF148 expression, and in turn, the depletion of ZNF148 leads to de-repression of ID1/3, which drives the cancer stem cell phenotype." (PMID 36207293, 2022). "Further work addressing both ZNF148 and ZNF281 within the same cellular context will be required to better understand the regulatory mechanisms contributing to the cancer stem cell state and metastatic progression." (PMID 36207293, 2022). "Although previous studies have not identified a specific role for ZNF148 in LGGs, its involvement in various other cancer types has been reported." (PMID 41007824, 2025). "Considering the ubiquitous nature of ZNF148 expression, the MYC, ZNF148, ID1/3 regulatory axis may be present in a broad array of cancers driven by MYC and ID proteins." (PMID 36207293, 2022).
cancer (continued). "For instance, the up-regulation of ZNF148 following knockdown of all other factors, including E4F1, could be a compensatory mechanism to up-regulate TERT expression, which is vital for unlimited cancer cell proliferation." (PMID 37918959, 2023). "Zinc finger protein 148 (ZNF‐148), also known as ZBP89, is a Krüppel‐type zinc finger transcription factor that has been reported to be involved in many biological processes related to cancer, and it acts as a transcriptional regulator to activate or repress gene expression." (PMID 37909239, 2023).
infection (4 papers, 2016 to 2020). The state of being infected such as from the introduction of a foreign agent such as serum, vaccine, antigenic substance or organism. "A motif associated with the transcriptional repressor zinc finger protein 148 (ZNF148), was significantly enriched in downregulated promoters, suggesting that ZNF148’s repressor activity increased post-infection." (PMID 28257516, 2017). "The results showed that DYRK1A, FAM135A, PLAG1, ZNF148, and PHC3 were obviously inhibited at infection times of 3 h, 6 h, and 9 h pi." (PMID 31784561, 2019). "Downregulation of 4 miRNA target genes, including PLAG1, ZNF148, PHC3, and DYRK1A, was first found in CVB3-infected cells, though 4 genes were associated with nonenterovirus replication and infection." (PMID 31784561, 2019).
ZNF148 also shares sentences with these, for which no sentence is quoted: gastric cancer (3 papers); anaemia (2); colon (2); colon adenoma (2); hepatocellular carcinoma (2); aneurysm (1); aortic aneurysm (1); atherosclerosis (1); autoimmune thyroid disease (1); bacterial infection (1); benign tumors (1); brain disorder (1); bronchopulmonary dysplasia (1); chronic prostatitis (1); colitis (1); colon polyps (1); diabetes (1); Familial adenomatous polyposis (1); intestinal tumor (1); liver cancer (1); metabolic syndrome (1); metastatic disease (1); non-small cell lung carcinoma (1); ovarian carcinoma (1); polyp (1); polyposis (1); Temple syndrome (1); uveal melanoma (1); viral infection (1); viral myocarditis (1).
A further 1 disease shares a sentence with ZNF148 in 1 paper.